CAPS (calcyphosine)
Diseases named in the same sentence as CAPS in open-access papers (continued):
Sharing a sentence is not in itself a finding about the gene and the disease.
tumor (10 papers, 2011 to 2025). "Collectively, these findings identify CAPS as a putative tumor suppressor, establish its prognostic value, and provide a foundation for CAPS-based diagnostic and therapeutic strategies." (PMID 41383604, 2025). "While previous studies have linked CAPS overexpression to stress-responsive or metabolically activated tumor states, our findings instead reveal an association with epithelial differentiation and suppression of proliferative capacity." (PMID 41383604, 2025). "Collectively, these multi-omics and multi-cohort analyses highlight the context-dependent role of CAPS across tumor types and underscore its potential utility as a molecular biomarker for precision oncology." (PMID 41383604, 2025). "Collectively, these results underscore the molecular heterogeneity of CAPS alterations across different tumor types and highlight the need for further mechanistic studies in specific tumor contexts." (PMID 41383604, 2025). "The results showed that all genes exhibited significant differential expression in tumor tissues; however, only four genes (CAPS, DAPK1, P4HA1, and PCED1A) demonstrated independent prognostic value." (PMID 40463370, 2025). "Collectively, these findings suggest that CAPS exerts tumor-suppressive effects not only by modulating cellular metabolism and differentiation but also by shaping the immune microenvironment, thereby providing new insights into its multifaceted role in EC." (PMID 41383604, 2025). "We next evaluated the correlation between CAPS expression and TMB as well as MSI, revealing tumor-type–specific associations." (PMID 41383604, 2025). "Quantitative Western blotting further confirmed elevated CAPS protein levels in tumor specimens (P < 0.01)." (PMID 41383604, 2025). "Mechanistically, CAPS appears to function as a tumor suppressor by promoting epithelial differentiation and oxidative metabolism, inhibiting aberrant proliferation, and modulating the immune microenvironment." (PMID 41383604, 2025). "FOXJ1 and CAPS expression levels also decreased with increasing tumor grade while PAX8 levels increased with tumor grade." (PMID 36552773, 2022). "Furthermore, CAPS-positive cells exhibited extensive crosstalk with immune cells, suggesting a potential role in facilitating anti-tumor immune responses." (PMID 41383604, 2025). "CAPS may act as a tumor suppressor in EC by stabilizing microtubule architecture, reprogramming cellular metabolism, and modulating immune interactions within the tumor microenvironment." (PMID 41383604, 2025). "Dysregulation of EF-hand-mediated calcium signaling and altered vesicular secretion may reshape the tumor microenvironment and modulate immune cell infiltration, suggesting a dual role for CAPS in calcium signaling and immune remodeling in EC." (PMID 41383604, 2025). "Notably, CAPS expression progressively declined with advancing tumor stage, suggesting its potential role in restraining disease progression." (PMID 41383604, 2025). "Unsurprisingly, CAPS+ cells were enriched in epithelial regions of tumor (29.9%)." (PMID 37694144, 2023). "In contrast, the LN229R group with concurrent FOSL1 knockdown and PRMT1 overexpression demonstrated accelerated tumor progression in comparison to the group featuring FOSL1 knockdown, PRMT1 overexpression, and CAPS knockdown." (PMID 41423530, 2025). "In summary, the following marker genes were used for subsequent analysis in supratentorial tumours: RELA, ELL3, FBP2, PCP4L1, and MYO3A for detection of RELA+ tumours; and MRAP, IGF1, CAPS, and WWC1 for detection of YAP1+ tumours." (PMID 34314101, 2021). "For instance, the expression of the ciliated epithelial markers, including FOXJ1, PIGR, CAPS, and GDF15, declined during the process of metastasis, although they were overexpressed in EC2 that mainly consisted of primary tumor cells." (PMID 34459128, 2021).
tumor (continued). "Taken together, these results delineate the immunological functions and communication features of CAPS at both single-cell and transcriptomic levels, providing novel insights into its regulatory role within the tumor immune microenvironment." (PMID 41383604, 2025). "IHC staining revealed significantly higher CAPS expression in tumor tissues compared to adjacent non-tumor counterparts." (PMID 41383604, 2025).
neurological disorders (1 paper, 2016). "This point towards a role of CAPs in neurological disorders." (PMID 27507934, 2016).
CAPS also shares sentences with these, for which no sentence is quoted: breast invasive carcinoma (1 paper); clear cell renal cell carcinoma (1); colorectal adenocarcinoma (1); focal segmental glomerulosclerosis (1); glioblastoma (1); gout (1); Hyperglycemia (1); infection (1); invasive carcinoma (1); ischemia (1); keratitis (1); lupus (1); lymphoma (1); malaria (1); mucinous ovarian carcinomas (1); serous ovarian carcinoma (1); type 1 interferonopathies (1); uterine corpus endometrial carcinoma (1); viral infection (1); viral pneumonia (1).